NCBP2AS2 (NCBP2 antisense 2 (head to head))
Synonyms: HIAR; KRASIM; NCBP2-AS2
Tractability: No criterion of Open Targets' tractability assessment is met for any kind of drug.
Gene: Protein-coding gene on chromosome 3 (196,942,674 to 196,943,543, forward strand). Ensembl gene ENSG00000270170.
Gene Ontology:
Molecular function: protein binding
Cellular component: mitochondrion
Homologues: Orthologues: chimpanzee NCBP2AS2 (100% identical), rabbit NCBP2AS2 (89% identical), pig NCBP2AS2 (87% identical), guinea pig NCBP2AS2 (85% identical), mouse Ncbp2as2 (73% identical), rat Ncbp2as2 (73% identical), tropical clawed frog ncbp2as2 (47% identical), zebrafish ncbp2as2 (44% identical), Drosophila melanogaster CG42518 (25% identical).
Diseases named in the same sentence as NCBP2AS2 in open-access papers:
NCBP2AS2 is named in the same sentence as 5 diseases in open-access papers, as found by Europe PMC text mining. Sharing a sentence is not in itself a finding about the gene and the disease. The quoted sentences say what the papers report.
hepatocellular carcinoma (4 papers, 2020 to 2024). A malignant tumor that arises from hepatocytes. "For instance, KRASIM, the microprotein coded by the lncRNA NCBP2-AS2 has been found to suppress expression of KRAS and inhibit ERK signaling in hepatocellular carcinoma cells." (PMID 35139853, 2022).
COVID-19 (1 paper, 2022). A disease caused by infection with severe acute respiratory syndrome coronavirus 2. "The present study aimed to identify the expression level of antisense lncRNAs (A2M-AS1, DBH-AS1, FLVCR1-DT, and NCBP2AS2-1) and FLVCR1 in COVID-19 patients and its relation to the severity of the disease." (PMID 36359290, 2022). "The expression levels of DBH-AS1, FLVCR1-DT, the antisense long non-coding RNA of FLVCR1 and NCBP2AS2-1, and the antisense long non-coding RNA of NCBP2 in COVID-19 patients in this study were deregulated, with a significant increase in both patient groups in comparison with controls." (PMID 36359290, 2022).
tumor (4 papers, 2019 to 2024). "In addition, hypoxic tumor-associated fibroblasts increase NCBP2-AS2/HIAR through an enhanced VEGF signaling pathway and promote endothelial cell sprouting." (PMID 36998056, 2023).
cancer (2 papers, 2022 to 2025). A tumor composed of atypical neoplastic, often pleomorphic cells that invade other tissues. "Nuclear cap-binding protein subunit-2 antisense RNA 2 (NCBP2AS2), also called the hypoxia-induced angiogenesis regulator (HIAR), is abundant in hypoxic cancer-associated fibroblasts (CAFs)." (PMID 36359290, 2022).
infection (1 paper, 2022). The state of being infected such as from the introduction of a foreign agent such as serum, vaccine, antigenic substance or organism. "The DBH-AS1, FLVCR1-DT, and NCBP2AS2-1 RNAs showed significantly higher levels in patients with moderate COVID-19 infection than controls, while patients with severe infection had significantly higher levels than both controls and patients with moderate infection (p =< 0.001 for all)." (PMID 36359290, 2022).